EZH2 (enhancer of zeste 2 polycomb repressive complex 2 subunit)
Diseases named in the same sentence as EZH2 in open-access papers (continued):
Sharing a sentence is not in itself a finding about the gene and the disease.
breast cancer (continued). "We found that in breast cancer patients, EZH2 expression scores correlated significantly with Ki-67 expression scores in both primary and metastatic lesions and Ki-67 expression and EZH2 expression scores were significantly higher in metastatic lesions compared with PBC lesions." (PMID 28241804, 2017). "However, the association between EZH2 expression in benign breast tissue and breast cancer risk has not previously been evaluated in a large prospective cohort." (PMID 28253895, 2017). "Moreover, NOTCH1 inhibition prevented EZH2-mediated CSC expansion in breast cancer." (PMID 28415635, 2017). "Therefore, EZH2 may represent a potential therapeutic target for this aggressive breast cancer that exhibits high expression levels of Ki-67, thus warranting further investigation." (PMID 28241804, 2017). "Furthermore, the information may facilitate our understanding of how to develop and use the EZH2 inhibitor as a single agent or in combination with other inhibitors for breast cancer treatment." (PMID 26868841, 2016). "Therefore, blocking EZH2 enzyme activity may present a valid therapeutic strategy for the treatment of cancers with EZH2 overexpression including breast cancers." (PMID 26868841, 2016). "Additionally, EZH2-stimulated epigenetic silencing contributes to constitutive activation of Wnt/β-catenin signaling and consequential cellular proliferation in hepatocellular carcinoma, gastric cancer, renal cell carcinoma, colon cancer and breast cancer." (PMID 27092879, 2016). "Since altering GSK3β activity affects the trimethylation of H3K27 and the expression of EZH2-targeted genes, and GSK3β-EZH2 interaction has been shown in nasopharyngeal cancer cells, we asked whether this interaction occurs in our system, including breast cancer and mammalian epithelial cells." (PMID 27494834, 2016). "In our study, EZH2 expression was found to be significantly and gradually increased from normal cervical tissues to cervical cancer in situ tissues and then to cervical cancer tissues, in agreement with the results of previous studies of cervical cancer, prostate cancer and breast carcinoma." (PMID 27092879, 2016). "Regarding predictive factors for breast cancer, high EZH2 expression was significantly associated with the absence of estrogen receptor (positive vs. negative: OR 0.15, 95% CI: 0.11–0.20) and progesterone receptor (positive vs. negative: OR 0.30, 95% CI: 0.23–0.39) expression." (PMID 25974088, 2015). "Additionally, EZH2 expression is required for pancreatic and breast cancer stem cell maintenance." (PMID 26484567, 2015). "Next we sought to determine whether NBAT1 regulates breast cancer cell invasion via EZH2." (PMID 26378045, 2015). "Moreover, simultaneous up-regulation of HOTAIR and EZH2 might be of clinically significance because a recent study of a breast cancer archive correlates simultaneous high expression of EZH2 and HOTAIR with aggressive tumor growth and metastasis." (PMID 26378045, 2015). "EZH2 has been reported to be up-regulated in metastatic prostate cancer relative to localised disease or benign prostatic hypertrophy, suggesting a potential involvement in prostate cancer progression, and its over-expression also correlates with breast cancer aggressiveness and poor prognosis." (PMID 25949794, 2014). "However, miR-214-3p has also been described to exert a tumor suppressor function in breast cancer cell lines, where reduced levels of this microRNA result in increased proliferation and invasion and in accumulation of EZH2, a polycomb group protein with the potential to promote cell proliferation." (PMID 24358187, 2013). "Importantly, it has been shown that BRCA1 (breast cancer early-onset 1) protein binding to PRC2 inhibits the binding of HOTAIR to the EZH2 component of PRC2, and abolishes HOTAIR-enhanced recruitment of PRC2 to its target HOX (homeobox) A9 gene promoter in human breast cancer cells and fibroblasts." (PMID 23875687, 2013).
breast cancer (continued). "EZH2 expression may also be triggered by hypoxia, a condition present in nearly all solid tumors: HIF1α-dependent transactivation of EZH2 was demonstrated in breast cancer-initiating cells." (PMID 23110793, 2012). "However, the observation that these two basal-like breast cancer cell lines are also sensitive to EZH2 inhibition, and the repeated observation that EZH2 overexpression characterizes basal-like breast tumors, warrants the further investigation of EZH2 as a druggable target." (PMID 19709408, 2009). "Our data show that BRCA1-deficient tumor cells are selectively dependent on EZH2 expression, and suggest that pharmacological disruption of EZH2 could provide another individualized approach for the treatment of BRCA1-mutated breast cancers, and possibly also for sporadic basal-like breast tumors." (PMID 19709408, 2009). "Finally, we identified a possible mechanism to explain why BMI1 overexpression may contribute to a better outcome than EZH2 overexpression in breast cancer." (PMID 19099573, 2008). "Interestingly, EZH2 was found to methylate cytoplasmic proteins involved in Akt-signaling, suggesting that the oncogenic role of EZH2 in breast cancer could also be unrelated to its role in epigenetic regulation." (PMID 19099573, 2008). "Another example is breast cancer, where the m6A reader protein YTHDF1 promotes osteolytic bone metastasis by enhancing the translation of EZH2 and CDH11." (PMID 40872531, 2025). "EZH2 promotes the transcriptional silencing of various genes by catalyzing H3K27 methylation, thereby inducing EMT and metastasis in breast cancer." (PMID 40006021, 2025). "In human breast cancer MCF-7 cells, dox-induced RAD51B knockout reduced AMPK phosphorylation and EZH2 phosphorylation at Thr311, leading to decreased ERα expression." (PMID 41318657, 2025). "Meanwhile, PRMT1 can facilitate the asymmetric methylation modification of EZH2, enhancing its protein stability and promoting the EMT process of breast cancer cells, which ultimately leads to breast cancer metastasis." (PMID 39890802, 2025). "Dio3os has an inverse correlation with EZH2 in prostate cancer (PRAD), breast cancer (BRCA), and glioblastoma multiforme (GBM) across various cell lines, underscoring the function of EZH2 in repressing Dio3os transcription." (PMID 41235096, 2025). "For instance, AMPK phosphorylated EZH2 at T311 to disrupt the interaction between EZH2 and SUZ12 thereby attenuating PRC2-dependent methylation of histone H3 at Lysine 27 in ovarian and breast cancer." (PMID 40289112, 2025). "Additional examples include miR-212, which modulates EZH2, G9a, and HDACs in lung cancer; miR-126, targeting HDAC2 in prostate cancer; and miR-34a, which regulates SIRT1 in breast cancer." (PMID 40761244, 2025). "Therefore, we speculated that EZH2 inhibited DPP4 expression in the breast cancer." (PMID 40708008, 2025). "Consistently, EZH2 inhibitors also blockaded H3K27me3 and induced re-expression of DPP4, which was initially suppressed by paclitaxel in breast cancer cell lines." (PMID 40708008, 2025). "EZH2 inhibitors have shown therapeutic promise not only in SCLC but also in other cancers, including prostate and breast cancer models, further supporting the rationale for their clinical evaluation." (PMID 41353272, 2025). "In a previous study, it was shown that CDYL2 recruits G9a and EZH2 to epigenetically repress miR124, which promotes NF-κB and STAT3 activation and negatively impacts the prognosis of breast cancer." (PMID 40843360, 2025). "Other miRNAs include miR-9-5p (HDACs in gastric cancer), miR-101 (EZH2 in glioblastoma), miR-22 (TIP60 and HDAC4 in breast cancer), and miR-125 (HDAC4 and HDAC5 in breast cancer)." (PMID 40761244, 2025). "MS1943, EZH2 degrader utilizing PROTAC technology, has demonstrated remarkable anti-tumor effects in prior studies on breast cancer and Burkitt’s lymphoma." (PMID 40308579, 2025).
breast cancer (continued). "To summarize, the silencing of both EZH2 and NIR can boost the expression of FOXO3 and suppress breast cancer cell proliferation." (PMID 40003882, 2025). "Previous studies have shown that EZH2 plays a crucial role in tumour resistance to chemotherapy including SCLC, breast cancer, ovarian cancer, and head and neck cancer." (PMID 38644473, 2024). "EZH2 was found to co-repress onco-suppressor genes with YAP also in Schwann cells and in breast cancer cells as well as inflammation-related genes in intestinal cells." (PMID 39455556, 2024). "The interplay between EZH2 and other cell cycle targets (e.g., AURKA, CHEK1, CDKN1A) has also been reported in other contexts such as breast cancer, melanoma, non-Hodgkin’s lymphoma, T-cell acute lymphoblastic leukemia." (PMID 38405800, 2024). "The pivotal roles of integrin α11, and EZH2, which regulates integrin α11 expression along with GLI-1, suggest them as potential targets for inhibiting drug-resistant breast cancer." (PMID 38664825, 2024). "Another study observed that EZH2-induced epigenetic silencing of miR-29b/miR-30d inhibited macrophage infiltration into the TME, thereby augmenting breast cancer progression." (PMID 38333212, 2024). "This may be explained by the fact that EZH2 and SUV39H1 regulate gene expression through the transfer of methyl groups to amino acid residues of histones, and their positive regulation has been linked in previous studies to aggressive breast cancer and a poor prognosis for breast cancer survival." (PMID 38929688, 2024). "In breast cancer, the oncoprotein-binding domain of Yin Yang 1 (YY1) has the ability to attract EZH2, leading to the downregulation of both phosphatase and tensin homolog (PTEN) and PTENP1." (PMID 38534385, 2024). "For example, the EZH2 PROTACs MS177 and MS8815 have been reported to be effective in inhibiting the growth of breast cancer cells and PROTAC EZH2 degrader-1 in increasing sensitivity to cisplatin, etoposide, and teniposide in small cell lung cancer (SCLC)." (PMID 39769907, 2024). "The significance of the overexpression of EZH2 and ITGA11 in cancer progression and aggressiveness was also confirmed in breast cancer patients, using Kaplan-Meier survival analysis on The Cancer Genome Atlas (TCGA) dataset." (PMID 38664825, 2024). "EZH2 can form a ternary complex with RelB and RelA, promoting the activation of NF-kB and its target genes such as IL-6 and TNF in ER-negative basal-like breast cancer cells." (PMID 39769907, 2024). "Integrin α11 which was consistently up-regulated by cooperative interactions of HIF1α, GLI-1, and EZH2 in a positive feedback circuit, resulted in drug resistance, CSC increase and EMT in breast cancer cells." (PMID 38664825, 2024). "In breast cancer (BC), the transcription of ITGB1 is activated by CDC42, FOXM1, HIF1α, and EZH2 to support the ability of BC cells to invade and spread." (PMID 38279122, 2024). "GlcNAcylation at S75 results in the stabilization of EZH2, repressing the expression of important tumor suppression genes, while O-GlcNAcylation at the S73, S84, S87, T313, and S729 residues may have several different functions in regulating breast cancer progression." (PMID 39769907, 2024). "RSV inhibits the enhancer of zeste 2 (EZH2) through dephosphorylation of extracellular regulated protein kinases (ERK1/2), thereby curbing the proliferation and growth of breast cancer cells." (PMID 39439517, 2024). "The phosphorylation mechanisms of EZH2 protein in eight cancer types (GBM, LIHC, LUAD, breast cancer, PAAD, HNSC, UCEC, COAD, and OV) were explored using the CPTAC dataset." (PMID 36545914, 2023).
breast cancer (continued). "In breast cancer cells, AMPK-mediated phosphorylation at T311 attenuates EZH2 enzymatic activity toward H3K2721, and p38-mediated phosphorylation at T367 stimulates EZH2 cytoplasmic localization and metastasis." (PMID 37069142, 2023). "In recent years, a series of adverse chain reactions of malignant tumor progression due to EZH2 overexpression were reported more frequently, including malignant tumors like HCC, gastric cancer, breast cancer, esophageal cancer and endometrial carcinoma." (PMID 37626362, 2023). "Phosphorylation of EZH2 at T435 and T487 by CDK1 and CDK2 epigenetically silences target genes in breast cancers." (PMID 37803297, 2023). "Consistently, the EZH2 gene transcript from Gene expression profiling interactive analysis (GEPIA2) dataset and TNMplot database also provide that higher level in breast cancer and metastasis specimens of EZH2 than normal mammary glands epithelium specimens." (PMID 37803297, 2023). "EZH2 was overexpressed in polyploid giant cancer cells (PGCCs), the latter being also triggered by HCMV infection in breast cancer which points toward a potential link between HCMV, PGCCs, and EZH2." (PMID 37147437, 2023). "EZH2 R342 can be methylated by PRMT1, which increases epithelial–mesenchymal transition (EMT) in breast cancer cells and predicts poor prognosis in breast cancer patients." (PMID 37143582, 2023). "Meanwhile, UXT is highly expressed in breast cancer and that UXT suppresses RND3 epigenetically by recruiting EZH2 in breast cancer." (PMID 37152054, 2023). "In breast cancer, this K29- and K33-specific DUB binds, deubiquitinates, and stabilizes the enhancer of zeste homologue (EZH2) catalytic component of the gene silencing Polycomb repressive complex 2 (PRC2) to promote growth, resulting in poor prognosis." (PMID 37892185, 2023). "Data shows that Patients with lower EZH2 expression had longer overall survival (OS), recurrence-free survival (RFS) and distant metastasis-free survival (DMFS) in total breast cancer dataset (HR = 1.56, p < 0.05; HR = 1.73, p < 0.05; HR = 1.71, p < 0.05)." (PMID 37803297, 2023). "In breast cancer, the lncRNA ANCR decreases metastasis by facilitating the degradation of EZH2, the catalytic subunit of the polycomb repressive complex 2 (PRC2)." (PMID 37369946, 2023). "The NSD3L isoform interacts with EZH2 and RNA polymerase II to influence H3K36me2/3‐dependent transactivation of genes, including those related to NOTCH signaling in breast cancer." (PMID 37062069, 2023). "The authors observed that EZH2 silenced PHACTR2-AS1 and it led to instability of ribosomal DNA, which promoted cancer cell proliferation and metastasis in breast cancer." (PMID 37369946, 2023). "Among the four subtypes (basal-like, Her2, Luminal A, and Luminal B) of breast cancer we investigated, TNBC showed the highest level of EZH2 expression." (PMID 36642705, 2023). "Downregulation of interferon-γ inducible protein 16 (IFI16), a direct target of EZH2, decreases stimulator of interferon genes (STING) activation and downstream CXCL10/11 expression in response to trastuzumab treatment in HER2+ breast cancer (BC)." (PMID 37198402, 2023). "To further investigate the relationship between EZH2 and SMAD3 methylation and phosphorylation in breast cancer, we performed IHC staining assays on breast carcinoma samples." (PMID 35085106, 2022). "To investigate the clinical impact of EZH2 on breast cancer progression, we used UALCAN and the Kaplan-Meier plotter to assess the relationship between cellular levels of EZH2 mRNA and different types of breast cancer patient outcomes." (PMID 35813302, 2022). "Studies have shown that the expression level of EZH2, the core catalytic subunit of PRC2, is positively correlated with tumor grade in prostate and breast cancers and PRC2 is initially thought to have an oncogenic function." (PMID 36076977, 2022).
breast cancer (continued). "Here, the authors show that EZH2 activates an integrin B1 and FAK signaling pathway in breast cancer cells, which activates TGFB signaling to drive metastasis in the bone." (PMID 35538070, 2022). "It has been suggested that UCA1 confers endocrine-therapy resistance through EZH2/p21 axis and the PI3K/AKT signaling pathway in breast cancer." (PMID 35949302, 2022). "Using two breast cancer cell lines, MCF-7 and MDA-MB 231, genistein influenced H3 and H4 histones on H3K27me3, H3K9me3, H3K4me3, H4K8ac, and H3K4ac marks, on six genes (EZH2, BRCA1, ERa, ERb, SRC3, and P300)." (PMID 35327559, 2022). "Since the EZH2-CCF-cGAS axis promotes breast cancer metastasis, EZH2i can inhibit breast cancer metastasis by regulating this pathway." (PMID 35163710, 2022). "Taken together, we identified a synthetic lethal interaction between EZH2 and ATM and propose this synergistic interaction as a novel molecular combination for the treatment of BRCA1-mutant breast cancer." (PMID 35715861, 2022). "By cooperating with DNMT1, EZH2 knockdown led to DNA demethylation and consequently upregulated miR-124-3p, which suppressed its target CCL2 expression in breast cancer cells, leading to TAMs M2 polarization restraint." (PMID 36038549, 2022). "EZH2-mediated SMAD3 K53/K333 methylation was upregulated and correlated with SMAD3 hyperactivation in breast cancer, promoted tumor metastasis, and was predictive of poor survival outcomes." (PMID 35085106, 2022). "Consistent with our anti-metastatic effect of EZH2 inhibitor, recent studies that tested the effect of EZH2 HMT inhibitor (GSK-126) against TNBC and luminal B breast cancer, respectively, also witnessed the robust anti-metastatic potential of EZH2 inhibitor." (PMID 36446780, 2022). "In breast cancer tissues, HDAC2 and EZH2 protein expression levels also were inversely correlated with levels of miR-148a expression." (PMID 35892859, 2022). "We also examined the correlation between the expression of EZH2 and the downstream effector PTHLH in bone metastasis tissues obtained from breast cancer patients in the GSE14020 dataset." (PMID 35538070, 2022). "Curiously, in breast cancer, ANCR expression is inactive, leading to hyperactivity of EZH2, which in turn sets up several repressive marks in tumor suppressor genes such as Hoxa10 or E-Cadherin, which are involved in progression and EMT signals." (PMID 35054945, 2022). "In summary, we report that EZH2 promotes the formation of CCF in breast cancer cells and activates the cGAS–STING pathway to promote breast cancer metastasis." (PMID 35163710, 2022). "Interaction of EZH2 with HOTAIR: The EZH2 Polycomb complex can interact with the long non-coding RNA HOTAIR, which is highly expressed in breast cancer metastases, and a small molecular weight inhibitor of this interaction has been developed." (PMID 35406676, 2022). "To interrogate the efficacy of HIF1α/HDAC1/EZH2 inhibitors in vivo, we used the immune-competent syngeneic 4T1 murine breast tumor model that closely mimics human TNBC breast cancer tumorigenesis." (PMID 35840558, 2022). "To further explore how EZH2 facilitates PTHLH and TGFβ signaling in breast cancer cells, we detected pS465/467-Smad2 and pT180/Y182-p38 MAPK levels in MDA-MB-231 sublines." (PMID 35538070, 2022). "However, the function of EZH2 in the vicious cycle of breast cancer bone metastasis is unknown." (PMID 35538070, 2022). "Our breast cancer data mining in the PAM50 subtypes of breast cancer cohort display a positive correlation between EZH2 and KRT14 expression selectively in basal breast cancer subtype (TNBC) among all breast cancer subtypes." (PMID 36446780, 2022). "Among other modes of action of Cur, the authors described its ability to downregulate EZH2 expression and to stimulate three major members of the MAPK pathway, JNK, ERK, and p38 kinase in breast cancer cell lines." (PMID 35327559, 2022).